GDF15 (growth differentiation factor 15)
Diseases named in the same sentence as GDF15 in open-access papers (continued):
Sharing a sentence is not in itself a finding about the gene and the disease.
colorectal cancer (continued). "Furthermore, we used IHC to measure the expression levels of ENO1, GDF15, and H3K18la in subcutaneous colorectal cancer tumors from various treatment groups; the results were in line with earlier studies." (PMID 40775002, 2025). "Taken together, NAG-1/GDF15 effectively inhibits colorectal cancer growth in vivo." (PMID 40316530, 2025). "Notably, more mature NAG-1/GDF15 was detected in the media than in the cell lysate across all four colorectal cancer cell lines." (PMID 40316530, 2025). "Additionally, data from public databases revealed that colorectal cancer patients with high NAG-1/GDF15 expression had better survival rates compared to those with low NAG-1 expression, as shown by TCGA data." (PMID 40316530, 2025). "Also, higher levels of serum GDF15 are also detected in colorectal cancer patients and positively correlate with the occurrence of liver metastasis." (PMID 40144214, 2025). "The interaction between ATF3 and GDF-15 also been reported in human colorectal cancer cells." (PMID 39000420, 2024). "AV-380 and Ponsegromab, also anti-GDF-15 antibodies, are under evaluation as potential therapies for cancer-induced cachexia in non-small cell lung, pancreatic, and colorectal cancer patients, as well as in metastatic colorectal cancer, through Phase I and II studies." (PMID 39000420, 2024). "In addition, TAMs induced by colorectal cancer in mice produce high levels of growth differentiation factor 15 (GDF15), which enhances β-oxidation of fatty acids, thereby reducing the chemosensitivity of colon cancer cells to 5-FU." (PMID 37004014, 2023). "Furthermore, increased circulatory levels of GDF15 are clinically related to cancer progression and chemotherapy resistance in ovarian, prostate, breast, and colorectal cancers." (PMID 36769245, 2023). "Furthermore, activation of TAS2R14 in a human colorectal cancer cell line is supposed to result in increased GDF15 levels, which is involved in several biological functions like anti-inflammatory and apoptotic pathways." (PMID 37286811, 2023). "It was demonstrated that GDF15 was overexpressed in colorectal cancer." (PMID 36532065, 2022). "In colorectal cancer, GDF15 regulated the TGF‐β/Smad2/3 pathway to facilitate tumor migration." (PMID 33098235, 2020). "In addition, GDF15 has been reported to enhance the migration of colorectal cancer cells and liver cancer stem‐like cells." (PMID 33098235, 2020). "Sera from patients with metastatic prostate, breast, and colorectal carcinomas validate this finding at protein level, which indicate that GDF-15 may be a biomarker for cancer." (PMID 32508832, 2020). "However, the role of growth differentiation factor 15 (GDF15) in colorectal cancer (CRC) metastasis and EMT remains poorly understood." (PMID 26497212, 2016). "After adjusting for common confounders, we observed direct associations of GDF-15 with lung cancer risk, NT-proBNP with breast, prostate and colorectal cancers, HbA1C with lung, colorectal, and breast cancer risks, and CRP with lung and colorectal cancer risks." (PMID 34935094, 2022). "Thus, for those agents that have benign side effect profiles, there might be potential that they could be used in combination with a GDF15 inhibitor for the prevention or treatment of colorectal cancer in the future." (PMID 31389184, 2019). "NAG-1/GDF15, a tumor suppressor, is synthesized as a pro-form in colorectal cancer (CRC) cells and undergoes cleavage to generate its mature form." (PMID 40316530, 2025). "Expression of both NAG-1/GDF15 WT and NAG-1/GDF15 R193A significantly suppressed β-catenin activity across different colorectal cancer cell lines." (PMID 40316530, 2025). "In colorectal cancer (CRC) patients, circulating GDF15 concentration has been observed to be elevated, and further increase when metastasis occurs, suggesting GDF15 is positively associated with metastasis of CRC." (PMID 40144214, 2025).
colorectal cancer (continued). "To determine if this phenomenon also occurs in colorectal cancer cell line SW480, we analyzed the ECM and observed that pro-NAG-1/GDF15 was present, whereas mature NAG-1/GDF15 was undetectable." (PMID 40316530, 2025). "There is evidence that the upregulation of NOX4, CXCL8, CXCL5, GDF15, and MMP13 genes in colorectal cancer promotes the metastasis of cancer cells, so a sustained upregulation of these genes after aspirin treatment will not benefit from treatment." (PMID 41425852, 2025). "Previous studies already showed that the bitter-tasting compounds diclofenac (TAS2R14) and resveratrol (TAS2R14, TAS2R39) increased the NSAID-activated gene (NAG-1), which was later renamed GDF15, in a human colorectal carcinoma cell line." (PMID 34784295, 2022). "Of the remaining inflammatory proteins, those that showed the strongest potential as future colorectal cancer biomarkers were AREG, LRG1 and potentially MIC-1/GDF15." (PMID 34503217, 2021). "In colorectal cancer, where clinical data have established a strong link between GDF-15 expression and poor survival, GDF-15 is reported to induce EMT-related factors and to enhance metastasis." (PMID 32508832, 2020). "In this study, we demonstrate that GDF15 plays an essential role in mediating hypoxia-initiated EMT and metastasis of colorectal cancer cells." (PMID 32076610, 2020). "Further study implicates that hypoxia-induced GDF15 is required for the EMT and invasion of colorectal cancer cells; enforced expression of GDF15 promotes the mitochondrial oxidation of fatty acids in colorectal cancer cells." (PMID 32076610, 2020). "Moreover, increased GDF-15 expression levels were markedly associated with unfavorable overall survival (OS) in patients with DST (HR = 2.34, 95% CI: 2.03–2.70, P < 0.001; I2 = 0.0%) and colorectal cancer (CRC) (HR = 2.27, 95% CI: 1.96–2.63, P < 0.001; I2 = 0.0%)." (PMID 30808336, 2019). "A recent study indicated that GDF15 promoted EMT and metastasis in colorectal cancer through binding to the TGF-β receptor to activate Smad2 and Smad3 pathways." (PMID 28199981, 2017). "Thus, GDF15 may promote colorectal cancer metastasis through activating EMT." (PMID 26497212, 2016). "To assess whether inhibiting these enzymes affects the pro-to-mature NAG-1/GDF15 ratio in colorectal cancer cell lines, we treated NAG-1/GDF15 WT stable cell lines with either a pan-MMP inhibitor or a pan-PCSK inhibitor." (PMID 40316530, 2025). "Pro-NAG-1/GDF15 was predominantly found inside the colorectal cancer cell lines, while mature NAG-1/GDF15 was minimally or not detectable intracellularly for both the WT and R193A." (PMID 40316530, 2025). "GDF15, a member of the TGF-β superfamily, is involved in multiple biological pathways, including the cytokine-cytokine receptor interaction pathway (hsa04060) and the colorectal cancer pathway (hsa05210)." (PMID 39108882, 2024). "The present investigation mainly focused on the ELFN1-AS1/GCN5-SND1/H3K9ac/GDF15 axis, but additional mechanisms involving ELFN1-AS1 may also exist in colorectal cancer (CRC)." (PMID 37147528, 2023). "For example, GDF15 is involved in the progression of esophageal squamous cell carcinomas, epithelial–mesenchymal transition (EMT) and metastasis in colorectal cancers, and an enhancement of the tumor-initiating and self-renewal potential of multiple myeloma cells." (PMID 32492819, 2020). "Interestingly, under hypoxia exposure, CHOP induced by PERK-eIF2α can bind to growth differentiation factor 15 (GDF15) and activate its transcription, regulating EMT and the metastasis of colorectal cancer cells." (PMID 33267910, 2020). "For instance, overexpression of GDF15 promotes EMT and metastasis of colorectal cancer cells." (PMID 33098235, 2020).
colorectal cancer (continued). "Notably, experimental and epidemiological evidence has demonstrated that GDF-15 levels are up-regulated in many types of DST, such as colorectal cancer (CRC), gastrointestinal cancer (GC), pancreatic cancer (PC), esophageal carcinoma (EC), and liver cancer." (PMID 30808336, 2019). "Since it is well known that GDF15 is a secreted protein, we used recombinant GDF15 protein (rhGDF15) to test whether GDF15 promoted EMT and metastasis through paracrine signal in colorectal cancer cells." (PMID 26497212, 2016). "Taken together, these data demonstrated that GDF15 could promote EMT and metastasis by autocrine and paracrine signaling pathways in colorectal cancer." (PMID 26497212, 2016). "Besides colorectal cancer cell lines, we found that NAG-1/GDF15 could decrease β-catenin and NF-κB activity in other types of cancer cell lines." (PMID 40316530, 2025). "Interestingly, unlike other colorectal cancer cells, Caco-2 cells appear to utilize this second site, as the NAG-1/GDF15 R193A construct did not prevent the production of the mature form." (PMID 40316530, 2025). "In addition, MSLN and GDF15 were found to be significantly upregulated (fold change = 12.24 for MSLN and fold change = 14.76 for GDF15) in colorectal cancer tissues, as well as to interact with colorectal-cancer-specific enhancers in colorectal cancer cells." (PMID 34361106, 2021). "GDF15, which is also known as Macrophage Inhibitory Cytokine 1 (MIC-1), has been shown to be upregulated in several aggressive tumor types such as glioblastoma, pancreatic, breast and colorectal cancers and it has been correlated with poor prognosis and patient survival." (PMID 30700740, 2019). "Treatment with the pan-PCSK inhibitor CMK led to an increase in pro-NAG-1/GDF15 levels, whereas the pan-MMP inhibitor GM 6001 did not produce this effect in colorectal cancer cells." (PMID 40316530, 2025).
Hypertension (73 papers, 2012 to 2025). The presence of chronic increased pressure in the systemic arterial system. "In a population-based prospective cohort study, circulating GDF-15 was significantly and positively associated with hypertension at baseline examination, and it was also an independent predictor of hypertensive heart failure during long-term follow-up." (PMID 40371061, 2025). "In conclusion, BS significantly reduces circulating GDF15 levels, particularly in patients with hypertension or T2D, indicating an association with clinical improvement after BS." (PMID 40530451, 2025). "This study represents the inaugural meta-analysis to quantify the association between circulating GDF-15 levels and the prevalence of hypertension." (PMID 40371061, 2025). "Our findings initially suggest that elevated GDF-15 levels are associated with a higher prevalence of hypertension." (PMID 40371061, 2025). "During weight loss, individuals with initial hypertension experienced an overall stronger decline of GDF15 levels despite largely congruent dynamics during the observed time span of 12 months." (PMID 36430499, 2022). "A genome-wide association study showed association of rs1059369 with GDF-15 expression, multiple myeloma, hypertension, hepatitis C virus infection." (PMID 35911685, 2022). "In this study, we found that plasma traumatic acid levels were associated with the presence of hypertension, higher preprandial plasma glucose and GDF‐15 levels, and impaired renal functions." (PMID 34939349, 2022). "Common risk factors for ICH and SAH, such as age, hypertension, and smoking, are also related to circulating levels of GDF-15 in elderly individuals." (PMID 34177769, 2021). "Despite the lack of prospective studies exploring the relationship between circulating GDF-15 and the risk of hypertension, the past dozen years have seen numerous studies providing information on hypertension prevalence across different GDF-15 concentration intervals in different populations." (PMID 40371061, 2025). "The GDF15-specific metformin effect was implied to increase hypertension risk in two MR analyses." (PMID 38012470, 2024). "GDF15 is presently considered to be a prognostic and diagnostic marker in several disease conditions, including pathologies involving vascular remodelling such as hypertension." (PMID 36992609, 2023). "Similarly, we demonstrated that plasma GDF‐15 levels are associated with the presence of hypertension, higher preprandial plasma glucose levels, lower haemoglobin and albumin levels, and impaired renal functions." (PMID 34939349, 2022). "However, the association of plasma GDF-15 levels with left ventricular hypertrophy (LVH) in hypertension is poorly understood." (PMID 23071585, 2012). "GDF-15 blood levels were proposed to be a clinically relevant biomarker within the context of MetS, as they have been associated with several MetS components, such as hyperglycemia, hypertension, and hyperlipidemia, high waist circumference, WHR and CRP, and low HDL-C." (PMID 38255954, 2024). "Also in a cohort of 3219 adults 30-65 years of age a high GDF-15-level was associated with age, hypertension, cardiovascular risk factors, cardiac and renal dysfunction, coronary calcification and was independently related to all cause and cardiovascular mortality during 7 years follow-up." (PMID 24312445, 2013). "A recent cross-sectional study showed that circulating GDF-15 levels were significantly higher in patients with grade 2 hypertension than those with grade 1 hypertension and healthy individuals." (PMID 40371061, 2025). "In the dose-response meta-analysis, the prevalence of hypertension increased by 24% with every 1 ng/ml increase in GDF-15 (OR 1.24, 95% CI 1.16–1.33, P < 0.001)." (PMID 40371061, 2025). "In our study, we observed a strong association between higher GDF-15 levels and cardiometabolic risk factors, including high triglycerides (TG), low high-density lipoprotein (HDL), and hypertension." (PMID 40722664, 2025).
Hypertension (continued). "The positive association between hypertension or CVD and risk of hospitalization or death was mediated 16.4% by TNFR1 and 12.0% by IL-6, as well as 12.4% by GDF15." (PMID 41280118, 2025). "This meta-analysis aimed to quantitatively evaluate the relationship between circulating GDF-15 and hypertension prevalence." (PMID 40371061, 2025). "As circulating GDF-15 concentration increased, the OR for hypertension prevalence increased, but after reaching approximately 5.5 ng/ml, the dose-response curve plateaued or even decreased slightly." (PMID 40371061, 2025). "In this population, compromised renal clearance capacity leads to progressive GDF-15 accumulation, which interacts bidirectionally with hypertension drivers such as sodium retention and fluid overload." (PMID 40371061, 2025). "The pooled result indicated that the prevalence of hypertension increased by 24% with each 1 ng/ml increase in circulating GDF-15 (OR 1.24, 95% CI 1.16–1.33, P < 0.001)." (PMID 40371061, 2025). "The positive association between hypertension or CVD and GDF15 was mediated 27.9% by TNFR1, 13.6% by IL-6, and 1.9% by TNF-a independently." (PMID 41280118, 2025). "Consequently, in CKD-associated hypertension, GDF-15 may exert its influence through multiple pathways, which encompass not only the regulatory mechanisms activated by renal impairment but also potential pharmacological mechanisms involving receptor desensitization and saturation." (PMID 40371061, 2025). "After BS, circulating GDF15 levels significantly decreased, particularly in patients with hypertension or type 2 diabetes (T2D)." (PMID 40530451, 2025). "While the dose-response characteristics identified in this study offer new insights into the role of GDF-15 in the pathophysiology of hypertension, the precise mechanisms remain to be elucidated." (PMID 40371061, 2025). "In this study, we performed a dose-response meta-analysis based on all eligible studies to quantitatively evaluate the relationship between circulating GDF-15 and the prevalence of hypertension." (PMID 40371061, 2025). "As a finding of questionable relevance, patients with hypertension had elevated CSF and serum levels of GDF15." (PMID 40820083, 2025). "Subsequent dose-response meta-analysis revealed that each 1 ng/ml increment in GDF-15 concentration corresponds to a 24% increase in hypertension prevalence." (PMID 40371061, 2025). "Based on the pooled analysis, participants in the high GDF-15 layer were 1.60 times more likely for incident hypertension compared with individuals in low GDF-15 layer (OR 1.54, 95% CI 1.37–1.88, P < 0.001)." (PMID 40371061, 2025). "In this regard, growth and differentiation factor 15 (GDF-15), a member of the transforming growth factor-β (TGF-β) superfamily, has been linked with several MetS pathologies, including T2DM, obesity, hypertension, and CVDs." (PMID 38255954, 2024). "Patients with arterial hypertension were characterized by significantly elevated basal serum concentrations of GDF15, which is in line with its property as a biomarker of epithelial stress and cardiovascular risk in previous studies." (PMID 36430499, 2022). "ROC curve analysis of both study sub-cohorts indicated that serum GDF15 is a moderately applicable marker for patients’ classification regarding hypertension (LCD: AUC = 0.716; RYGB: AUC = 0.689)." (PMID 36430499, 2022). "Consistent with previous studies, we herein found that the serum GDF15 level is associated with higher WC, HC, HbA1c, and a higher prevalence of T2DM and hypertension." (PMID 35683420, 2022). "Forward linear regression analysis showed that age, gender, smoking and systemic hypertension were significant confounders affecting GDF-15 levels." (PMID 34048486, 2021). "A correlation between GDF-15 and blood pressure c.q. hypertension also has been reported previously." (PMID 34048486, 2021).